BOLA2B (bolA family member 2B)
Description:
Acts as a cytosolic iron-sulfur (Fe-S) cluster assembly factor that facilitates [2Fe-2S] cluster insertion into a subset of cytosolic proteins. Acts together with the monothiol glutaredoxin GLRX3.
Tractability: PROTAC: ubiquitination databases record sites on it.
Gene: Protein-coding gene on chromosome 16 (30,192,930 to 30,194,306, reverse strand). Ensembl gene ENSG00000169627.
Subcellular location: Cytoplasm; Nucleus
Subcellular location (Human Protein Atlas): Nucleoplasm
Pathways (Reactome):
Immune System: Gene and protein expression by JAK-STAT signaling after Interleukin-12 stimulation
Gene Ontology:
Molecular function: protein binding; iron-sulfur cluster binding; 2 iron, 2 sulfur cluster binding
Biological process: [2Fe-2S] cluster assembly; cell redox homeostasis; intracellular iron ion homeostasis; iron-sulfur cluster assembly; protein maturation
Cellular component: cytoplasm; iron-sulfur cluster assembly complex; nucleus; cytosol
Homologues: Orthologues: chimpanzee BOLA2B (98% identical), macaque BOLA2B (98% identical), dog BOLA2B (93% identical), pig BOLA2B (91% identical), rat Bola2 (88% identical), rat Bola2-ps1 (88% identical), guinea pig Bola2b (87% identical), mouse Bola2 (87% identical), rat AABR07034928.1 (78% identical), tropical clawed frog bola2 (76% identical), zebrafish BOLA2B (58% identical), Drosophila melanogaster CG33672 (47% identical). Paralogues in human: BOLA2 (100% identical), BOLA1 (43% identical), BOLA3 (26% identical).
Diseases named in the same sentence as BOLA2B in open-access papers:
BOLA2B is named in the same sentence as 7 diseases in open-access papers, as found by Europe PMC text mining. Sharing a sentence is not in itself a finding about the gene and the disease. The quoted sentences say what the papers report.
hepatocellular carcinoma (2 papers, 2023 to 2024). A malignant tumor that arises from hepatocytes. "The gene BOLA2B was reported to associate with human hepatocellular carcinoma progression and the BOLA2B-knockout mouse model showed a slow tumourigenicity." (PMID 38778183, 2024).
breast carcinoma (1 paper, 2023). "Decreased BOLA2B expression induced the proliferation of breast cancer cells and G2/M cell cycle arrest." (PMID 36923798, 2023).
gastric cancer (1 paper, 2023). A primary or metastatic malignant neoplasm involving the stomach. "Essentially, it was observed that BOLA2B was highly expressed in tumor tissues, except for gastric cancer and LIHC." (PMID 36923798, 2023).
cancer (3 papers, 2020 to 2025). A tumor composed of atypical neoplastic, often pleomorphic cells that invade other tissues. "The relationship between single-nucleotide variants (SNVs) and BOLA2B expression was also examined in the different cancers." (PMID 36923798, 2023). "Here, pan-cancer analysis was conducted to determine the expression patterns of BOLA2B and its impact on immune response, gene mutation, and possible molecular biological mechanisms in different tumors, together with investigating its potential usefulness for cancer prognosis." (PMID 36923798, 2023). "It was also found that BOLA2B induced the G2/M cell-cycle arrest, thus reducing cancer cell proliferation." (PMID 36923798, 2023). "Correlations between genes involved in m1A, m5C, and m6A modifications and BOLA2B mRNA expression were present in numerous cancers." (PMID 36923798, 2023). "Kaplan–Meier curves were used to evaluate differences in OS between the high- and low-BOLA2B subgroups in different types of cancer." (PMID 36923798, 2023). "Post-transcriptional modifications, including m5C, m1A, and m6A, were observed to regulate BOLA2B expression in all cancers." (PMID 36923798, 2023). "In this study, it was found that BOLA2B was highly expressed in a variety of human cancers, and its expression was correlated with immune infiltration." (PMID 36923798, 2023). "In the Hep3b cell line, knockdown of BOLA2B reduced the level of iron staining, indicating that BolA2 plays a key role in iron homeostasis in cancer cells." (PMID 36923798, 2023). "As regards to immune infiltration, BOLA2B expression tended to be negatively correlated with both immune cells and immune-related molecules, including cytokines, except in some cancers." (PMID 36923798, 2023). "Further investigation into BOLA2B’s role and molecular functions in cancer would provide new insights for cancer diagnosis and treatment." (PMID 36923798, 2023). "Kaplan–Meier plots showed the specific survival probability for every significant cancer influenced by BOLA2B expression." (PMID 36923798, 2023). "Here, we attempted to elucidate a comprehensive view of the role of BOLA2B in pan-cancer in terms of expression patterns, RNA modification, mutant profiles, and its relationships with immune-related factors and cancer prognosis." (PMID 36923798, 2023). "Since knockdown of BOLA2B reduced cancer cell proliferation, we assumed that it would affect the cell cycle." (PMID 36923798, 2023). "The percentages of each type of BOLA2B CNVs in the 33 cancers were then plotted and illustrated in a pie chart." (PMID 36923798, 2023). "Our findings suggested that BOLA2B plays important roles in multiple tumors and represents a promising therapeutic target for cancer treatment." (PMID 36923798, 2023). "Furthermore, the expression of BOLA2B is negatively correlated with immune cell infiltration in most cancers." (PMID 40361395, 2025). "We analyzed BOLA2B mRNA expression between tumor and normal tissues in 33 cancer types." (PMID 36923798, 2023). "Our study provides new insights into this recently discovered gene and suggests that BolA2B may be a promising novel target for the treatment of various cancers." (PMID 36923798, 2023). "In addition, we evaluated the effects of BOLA2B on the immune response in 33 cancers using the ESTIMATE algorithm." (PMID 36923798, 2023). "Paired comparisons also verified that BOLA2B was a cancer-related factor." (PMID 36923798, 2023). "Last, we performed the IHC staining of BolA2B in pan-cancer tissue samples." (PMID 36923798, 2023). "We then evaluated the prognostic significance of BOLA2B in pan-cancer analysis." (PMID 36923798, 2023).
cancer (continued). "However, even though methylation has been found to be important in the development of some cancers, BOLA2B methylation had little effect on the expression of the gene." (PMID 36923798, 2023). "This suggests that BOLA2B may have different functions in different cancer types." (PMID 36923798, 2023). "Further analysis revealed that of all cancers, UVM showed the highest correlation with BOLA2B expression, in both the immune and stromal scores." (PMID 36923798, 2023). "The most frequent cMDT disrupting interactions in over 90% of samples of a cancer type were those from the genes USP46, WDR74, RPS19, BOLA2B, NDUFA9, and LAMA3." (PMID 32879328, 2020). "Regarding m6A, the writer gene KIAA1429 was positively correlated with BOLA2B across all cancers, while other m6A writer genes showed negative correlations with BOLA2B in most cancers." (PMID 36923798, 2023). "In addition, our results showed that BOLA2B expression did not correspond with “Immune Hot” or “Immune Cold” cancer." (PMID 36923798, 2023).
tumor (3 papers, 2022 to 2023). "The ESTIMATE score of UVM tumor was strongly associated with BOLA2B expression, in contrast to other tumors, such as DLBC, READ, and LUSC, where negative correlations were observed." (PMID 36923798, 2023). "Many of these (DLK1, GAB2, BOLA2B, AOX1 and AGER) were closely related to cell proliferation and tumor progression, and associated with poor prognosis in HCC." (PMID 35331184, 2022). "We analyzed the effects of BOLA2B expression on tumor purity." (PMID 36923798, 2023).
BOLA2B also shares sentences with these, for which no sentence is quoted: liver cancer (1 paper); ovarian carcinoma (1).